CCR2 (C-C motif chemokine receptor 2)
Diseases named in the same sentence as CCR2 in open-access papers (continued):
Sharing a sentence is not in itself a finding about the gene and the disease.
tumor (continued). "The immunohistochemical analysis and flow cytometry results confirmed that FAM171B overexpression significantly increased macrophage infiltration in tumor tissues and that CCR2 inhibitor treatment effectively suppressed this effect." (PMID 37915048, 2023). "After CSF1R and CCR2 antagonism, they confirmed a significant reduction in tumor infiltrating monocytes and macrophages and found that tumor size decreased, an enhanced response to chemotherapy, and that hepatic and peritoneal metastasis decreased." (PMID 37575220, 2023). "To gain insight on the biological relevance of CCR2+ monocytes, we used a CCR2 depleting antibody MC-21 in our therapeutic tumor setting." (PMID 37849753, 2023). "The concentration of CCL2 in BC patients increased with advancing tumor stage, while the median level of CCR2 decreased with advancing stage." (PMID 37208442, 2023). "Macrophage membranes contain α4 integrin and CC chemokine receptor 2 (CCR2), making them ideal candidates for tumor targeting, and have been successfully used in bionic systems for drug delivery to tumor or inflammatory sites." (PMID 37765212, 2023). "In a model of Hepa 1-6 cell-derived liver tumors, developed in otherwise unchallenged mouse livers, CCL2/CCR2 blockade attenuated tumor growth, altered TAM phenotype and restored CD8+ T cell activity." (PMID 36845555, 2023). "Our results here indicate that angiotensin inhibition not only reduces the presence of CCR2-positive TAMs and other pro-tumor myeloid cells but also reprograms the compartment to an anti-tumor phenotype." (PMID 36724255, 2023). "Chemokine CCL2 can recruit monocytes with highly expressed CCR2, while targeted inhibition of CCR2 can decrease the recruitment of M2 macrophages and induce tumor infiltration of activated CD8+ T cells." (PMID 37494663, 2023). "Taken together, the findings highlight the role of CCR2+ tumor-infiltrating monocytes in contributing to a tumor-promoting microenvironment." (PMID 37849753, 2023). "CCR2 exists on the surface of a variety of immune cells and can guide immune cells to reach inflammatory and tumor sites." (PMID 36969169, 2023). "We assessed the presence of BMDMs using the CCR2 marker in sections from both the control and caALK5 tumor liver metastasis." (PMID 37240029, 2023). "They found that the splenic stromal cells of tumor-bearing mice recruited specific subsets of HSPCs into peripheral circulation via the CCL2/CCR2 axis." (PMID 37415162, 2023). "Depletion of CCR2+ cells with specific antibodies resulted in prolonged survival revealing CCR2+ monocytes as important for tumor immune escape in the TME." (PMID 37849753, 2023). "Our data show a new role of CCL2 as an angiocrine factor of the tumor microenvironment which suppresses tumor progression by directly acting through CCR2 expressed by tumor cells." (PMID 36374225, 2023). "These included B cells (BC_IGHG1_PRDM1), fibroblasts (FB_CALB2, FB_CFD, FB_COL27A1, FB_COMP, FB_MYH11, FB_RGS5, FB_SERPINE1), myeloid cells (M_CCL18, M_CCR2, M_CD14), and tumour cells (Tum_KRT6A, Tum_TNNT2)." (PMID 37370765, 2023). "This enables protection against tumors by therapeutic immune control of solid tumors and highlights the immunosuppressive influence of tumor infiltrating CCR2+ monocytes that need to be inactivated in addition for successful cancer immunotherapy." (PMID 37849753, 2023). "In OC patient, CCL2 is overexpressed in primary tumor cells and its receptor, CCR2, has been observed in TAMs isolated from OC patients." (PMID 37932814, 2023). "DSF has been reported to inhibit the interaction of FROUNT with CCR2 and CCR5, which decreases tumor associated macrophage (M2) accumulation in the TME, thereby decreasing tumor-promoting properties of tumor associated macrophage." (PMID 37376016, 2023). "GEM treatment significantly increased accumulation of CCR2+ macrophages and monocytes in the lungs of tumor-bearing as well as tumor-free mice." (PMID 36976637, 2023).
tumor (continued). "Therapeutic blocking of the CCL2/CCR2 axis counteracts the tumor-induced immunosuppression and leads to the activation of a CD8+ T cell anti-tumor response, attributed to the inhibition of MoMF infiltration and TAM polarization." (PMID 36845555, 2023). "The CCL2/CCR2 signaling pathway contributes to tumor-promoting myelogenesis by enhancing splenic EMH and substantially promotes the migration and accumulation of MDSCs in tumor tissues." (PMID 37415162, 2023). "Of all chemokines assayed, the CCR2/CCR4 ligand CCL2 was the most abundant chemokine detected in tumour biopsy, CUSA and cultured GNS cell supernatants, and was present above the limit of detection in all samples analysed." (PMID 35464424, 2022). "It showed that the expression of CSF2RB in tumor tissues was significantly lower than normal tissues, while the expression of CCR2 remained the same in the two different tissues." (PMID 35574409, 2022). "Deeper insight into the potential mechanisms of the CCL2/CCR2 axis in tumor progression and treatment will provide new directions for a better understanding of malignancies." (PMID 35702353, 2022). "Data obtained with a single CCR2 inhibitor however showed that the complex chemokine crosstalk would require targeting multiple chemokines for anti-tumor efficacy." (PMID 36613562, 2022). "In vivo, CCR2+ macrophages have been detected to localize close to endothelial cells at the border of the HCC tumor to initiate angiogenesis." (PMID 35409139, 2022). "We further demonstrate that the cells responsible for tumor control are mainly trained CCR2+ myeloid-derived cells." (PMID 35140221, 2022). "Monocytes have been considered as the precursors of TAMs for many years since CCL2/CCR2 signaling which recruits monocytes from bone marrow to tumor facilitates breast cancer metastasis." (PMID 36035994, 2022). "Given the potential role of MSMP/CCR2 in TAM recruitment in the tumor microenvironment, we analyzed CCR2 expression across immune cells with use of the DICE database." (PMID 35094142, 2022). "Tumors admixed with CCR2+ cells were smaller than those that were admixed with CCR2− cells, further supporting that the trained CCR2+ myeloid cells themselves are a primary effector cell in the anti-tumor mechanism." (PMID 35140221, 2022). "Tumor-derived CCL2, in combination with CCR2 on the surface of monocytes, recruits monocytes to infiltrate the tumor microenvironment or metastatic locations and promotes the TAMs to polarize into M2-TAMs." (PMID 36403055, 2022). "Another study showed that the combination of CCR2 and immune checkpoint inhibitors reduces tumor growth in cutaneous T-cell lymphomas." (PMID 36578079, 2022). "Next, we examined the potential cellular targets of CCR2/5i in the TME of the orthotopically implanted KPC tumor model." (PMID 35404390, 2022). "We found that although the addition of GVAX to RT + αPD-1 + CCR2/5i conferred early tumor control, tumor growth appeared to accelerate later in the disease course for reasons that remain to be further investigated." (PMID 35404390, 2022). "The CCL2/CCR2 signal pathway plays an essential role in monocyte recruitment toward the tumor niche." (PMID 35600367, 2022). "This highlights the role of the CCL2/CCR2 axis in the tumor microenvironment in stimulating PCa expansion and metastasis." (PMID 35406450, 2022). "The most studied signaling axis in this context has been the CCL2/CCR2, as CCR2 is highly expressed in tumors and have been shown to stimulate macrophages recruitment in the tumor microenvironment." (PMID 35757002, 2022). "Nitration of CCL2 (N-CCL2) through reactive nitrogen species within the tumor was shown to decrease its affinity to the receptor CCR2." (PMID 36366354, 2022). "The signalling axis of chemokine (C-C motif) ligand 2 (CCL2)–C-C chemokine receptor type 2 (CCR2) suppresses tumour metastasis through reduced angiogenesis in preclinical models." (PMID 36551788, 2022).
tumor (continued). "A natural CCR2 antagonist (from Abies georgei and named 747) showed anti-tumor activity in mouse models of HCC." (PMID 36679900, 2022). "So far, only a few studies explored the potential of PET imaging of CCR2-expressing macrophages in tumor models." (PMID 35526184, 2022). "For instance, C-C motif chemokine ligand 2 (CCL2) is upregulated in tumor cells following RT, and hence, leads to the corecruitment of tumor-associated macrophages, as well as Tregs, through the CCL2/chemokine receptor 2 (CCR2) axis." (PMID 36139006, 2022). "Second, we pharmacologically blocked myeloid cell migration into the tumor using a combination of CCR2 (BMS CCR2) and CXCR2 (SB225002) chemokine antagonists." (PMID 36104342, 2022). "CCL2 mediates tumor cell metastasis by binding to CCR2 on tumor cells and induces the expression of matrix metalloproteinase-9 (MMP-9) to increase the invasiveness of tumor cells." (PMID 35320940, 2022). "Influenced by the tumor microenvironment, and through the production of specific chemokines such as CCL-2, CCL-7 or CCL-12, MSCs are able to recruit CCR2 expressing monocytes to tumor sites, promoting the local concentration of macrophages and tumor growth." (PMID 35214113, 2022). "Initial studies inhibiting CCR2 by the use of antibodies have shown reduced tumour growth and improved efficacy of chemotherapies in multiple murine tumour models." (PMID 36497148, 2022). "It has been shown that the tumor stroma produces chemokine CCL2 to increase the release of CCR2+ inflammatory monocytes that infiltrate to tumor microenvironment." (PMID 36497393, 2022). "Compared to the control group, the number of tumors and the maximum tumor volume were reduced following intraperitoneal injection of CCR2 and CXCR2 antagonists for 6 weeks." (PMID 36403057, 2022). "Classical CD14+CCR2+ monocytes infiltrate neoplasms and contribute to the majority of myeloid cells within the tumor microenvironment, but they are eventually reprogrammed into pro-tumoral monocyte-derived cells by the cancer niche." (PMID 35493454, 2022). "The CCL2/CCR2 axis is implied in the proliferation, invasion, and angiogenesis of tumor cells and recruitment of immunosuppressive cells." (PMID 35702353, 2022). "In a recent study, it was proven that CCR2 is involved in the recruitment and initiation of tumor-promoting inflammation." (PMID 35592338, 2022). "In another study, CCR-2 dependent recruitment of macrophages by resident CAFs was reported to support tumor growth." (PMID 36117852, 2022). "Both TCGA and GEO data showed a good predictive value, and four genes (GIMAP6, CD80, IL16, CCR2) contributed the most to predicting tumor purity." (PMID 35280857, 2022). "Tumors in Ccr2 knockout mice are minimally infiltrated by MDSCs, which results in reduced tumor growth and metastasis." (PMID 33603130, 2022). "In a mouse lymphoma model, following co-culturing with TA-MSCs, BM-MSCs acquire a tumor­promoting phenotype that depends on the recruitment of macrophages to tumor sites mediated by CCR2." (PMID 36324128, 2022). "Results of qRT-PCR partially demonstrated the bioinformatics results that the mRNA levels of CXCL10, CXCL9, CCL5, and CCR2 were remarkably elevated in tumor tissues collected from PTC patients coexistent with HT than those without HT (P < 0.001)." (PMID 36266640, 2022). "In particular, CCL2 release by cancer cells leads to the recruitment not only of tissue-resident macrophages but also of CCR2+ Ly6C hi monocytes from the bloodstream that extravasate into tumor sites and differentiate into TAMs." (PMID 35664746, 2022). "In contrast to monocytes, neutrophils recruited through this axis displayed anti-tumor activity due to their CCR2-dependent ability to produce oxygen radicals that kill tumor cells." (PMID 35158948, 2022). "Firstly, we pretreated the BM cells with a CCR2 antagonist RS 102895 and evaluated BM cell migration to the tumor/stroma cocultures (HSC-2 + HDF, HSC-2 + PDS1, and HSC-2 + PDS2)." (PMID 34874922, 2022).
tumor (continued). "Through immunohistochemical staining sections of tumor tissues and adjacent tissues, we observed that the number of CCR2 positive cells in tumor tissues was more than that in adjacent tissues." (PMID 36497150, 2022). "CCR2 is expressed on the surface of multiple cell types, monocytes, dendritic cells, immune cells, natural killer cells, and tumor cells." (PMID 36403055, 2022). "In breast cancer models, removing CCR2 blockade induces tumor progression, migration, and angiogenesis." (PMID 36303138, 2022). "While CLL depleted both monocytes and F4/80+ macrophages, anti-CCR2 selectively eliminated monocytes in blood, spleen, and tumor." (PMID 36536097, 2022). "We note that the observed decrease in neutrophils in autochthonous disease is in contrast to findings observed with grafted tumor systems using a distinct CCR2 inhibitor." (PMID 36256464, 2022). "Compared with control meso CAR T cells, those with CCR2 coexpression showed a 12.5-fold increase in tumor infiltration in a mouse xenograft tumor model." (PMID 36419115, 2022). "In a murine breast cancer model, blocking CCR2 with RS504393 decreases the tumor growth in the presence of anti-PD-1." (PMID 36429101, 2022). "Histological analysis of double-K/O tumors presented decreased tumor-associated CCR2 and CCR4 expression and poor macrophage-associated (F4/80+ cells) CCR2+ expression." (PMID 35980743, 2022). "Anti-PD-L1 drugs and small molecule CCR2 antagonists that deplete M2-like TAMs play a synergistic effect and reduce tumor survival." (PMID 35672862, 2022). "Knocking down CCR2 or blocking CCL2/CCR2 signaling with CCR2 antagonists can inhibit tumor growth and metastasis, reduce postoperative recurrence, and improve survival." (PMID 36225938, 2022). "The CCR2 blocking technique has already been employed but, it can, unfortunately also impede TILs recruitment to the tumor bed." (PMID 35211124, 2022). "The role of C-C motif chemokine receptor 2 (CCR2) seems to influence TAM recruitment at the tumor site." (PMID 35592338, 2022). "The inflammatory monocytes CCR2+Ly6C+, after differentiating into Ly6C− macrophages, accelerate tumor cell extravasation by generating VEGF." (PMID 35664746, 2022). "This is directly demonstrated by our admix experiment where mice that received CCR2+ myeloid cells from WGP-trained mice showed a significantly reduced tumor burden as compared to mice that received CCR2- myeloid cells from the same trained mouse." (PMID 35140221, 2022). "Targeting TAMs by inhibiting CCR2 decreased the tumor-initiating cells, resulting in metastasis inhibition and enhancement of the anti-tumor T cell responses in pancreatic tumor and liver cancer." (PMID 35585567, 2022). "Here, we defined a recruitment coefficient σ as σ = (GFP volume) / (tumor volume) to quantify the ability of colorectal cells to recruit CX3CR1+CCR2+ macrophages per unit tumor volume." (PMID 35910800, 2022). "According to single-cell RNA sequencing (scRNA-seq), Apoe deletion was correlated with the decline of C1QC+ and CCR2+ macrophage within tumor infiltration, and mass spectrometry results noticeably showed down-regulated the number of M2 macrophages as well." (PMID 36147474, 2022). "We showed that MAMs differentiate from circulating classical Ly6C+ CCR2+ monocytes (CMs) that are recruited to the metastases by tumor-cell-derived CCL2." (PMID 36077870, 2022). "Blocking the CCL2/CCR2 axis was reported to be effective in reducing MDSCs and tumor growth in different preclinical models." (PMID 35158779, 2022). "The C‐C motif chemokine ligand 2 (CCL2)/C‐C motif chemokine receptor 2 (CCR2) signaling pathway is widely believed to play an important role in recruiting TAMs, subsequently contributing to tumor progression." (PMID 36698392, 2022).
tumor (continued). "Many preclinical studies showed high efficacy of CCL2/CCR2 antagonists; for instance, targeting CCR2 with a small-molecule inhibitor not only reduced recruitment of M2-type macrophages but also induced tumor infiltration of activated CD8+ T cells." (PMID 35592338, 2022). "Since this cell population also expresses CX3CR1, migration of bone marrow-derived cells from tumor-bearing Ccr2+/RFP/Cx3cr1+/GFP mice to soluble CX3CL1 was assessed." (PMID 36685592, 2022). "In order to reduce TAM accumulation at the tumour site, antagonists against chemokine receptors, such as CCR2, have been developed." (PMID 36497148, 2022). "CCR2 inhibition resulted in a larger number of tumour cells at d3 and more extensive vascularisation at d21 than observed in the other groups." (PMID 36241867, 2022). "PDAC highly expresses the CCL2 chemokine which leads to mobilization of CCR2+ monocytes from the bone marrow to the tumor." (PMID 36077755, 2022). "In patients who had increased expression of CCR2 and CCR5 in myeloid cells after receiving combination therapy with GVAX and αPD-1, the tumor-infiltrating myeloid cells were associated with increased M2-like macrophage and M-MDSC gene signatures." (PMID 35404390, 2022). "Ccr2 is a chemoreceptor necessary for monocytes/macrophages to migrate towards Ccl2, a chemokine produced by a variety of cells, including tumor cells." (PMID 36376929, 2022). "It is also notable that although the recruitment effect of YAP1 depends on the interaction of CCL2 and its receptor CCR2 on TAMs, other CCR2+ cells have the opposite effect, which is tumor suppression." (PMID 35672802, 2022). "Pharmacologic or genetic targeting of CCR2-expressing cells via a CCR2 antagonist or gene deletion limited the presence of these cells within the tumor and promoted their sequestration within the bone marrow." (PMID 36685592, 2022). "The chemokines CCL2 and CCL7, which are known as ligands of CCR2, promote the invasion and metastasis of tumor cells and induce immunosuppression." (PMID 35320940, 2022). "Despite being predominantly an M1-inducing factor, GM-CSF can induce the production of CCL2 from T cells in the tumor microenvironment and the expression of CCR2 on macrophages thus polarizing them to the metastasis-promoting the M2 phenotype." (PMID 35865534, 2022). "As revealed from the results, Apoe deletion was correlated with a decline of C1QC + and CCR2+ macrophages in tumor infiltration." (PMID 36147474, 2022). "Macrophages are a major component in the tumor microenvironment arising from spinal marrow-derived monocyte differentiation in response to CC chemokine 2 (CCL2/CCR2) and colony-stimulating factor 1 (CSF-1/CSF-1R)." (PMID 36246916, 2022). "In line with expectations, it has been observed that the tumor progression promoting and MDSC recruiting effects of FAP+ CAFs are abolished in Ccr2-deficient mice." (PMID 36263225, 2022). "It should be noted that, although addition of GVAX to RT + αPD-1 + CCR2/5i conferred early tumor control, tumor growth appeared to accelerate later in the disease course." (PMID 35404390, 2022). "Overall, both PET tracers based on the ELCi molecule demonstrated specific binding to CCR2, but only [64Cu]Cu@CuOx-ELCi was tested in tumor-bearing mice." (PMID 35526184, 2022). "Blocking CCL2/CCR2 axis reverses MDSCs infiltration into the tumor, augmenting the effectiveness of the cancer immunotherapy." (PMID 36303138, 2022). "Tumor-derived CCL2 was shown to mediate resistance to radiation by recruiting CCR2+ monocytes in a mouse model of PDAC." (PMID 35404390, 2022). "Accordingly, CCR2 inhibitors reduce the infiltration of immunosuppressive myeloid cells limiting both primary tumor growth and metastasis spreading." (PMID 35158779, 2022). "This bone marrow population expands in tumor bearing mice and pharmacological or genetic disruption of CCR2 promotes the sequestration of these cells in the bone marrow." (PMID 36685592, 2022).